KRTAP26-1 (keratin associated protein 26-1)
Description:
In the hair cortex, hair keratin intermediate filaments are embedded in an interfilamentous matrix, consisting of hair keratin-associated proteins (KRTAP), which are essential for the formation of a rigid and resistant hair shaft through their extensive disulfide bond cross-linking with abundant cysteine residues of hair keratins. The matrix proteins include the high-sulfur and high-glycine-tyrosine keratins.
Tractability: No criterion of Open Targets' tractability assessment is met for any kind of drug.
Gene: Protein-coding gene on chromosome 21 (30,319,124 to 30,320,315, reverse strand). Ensembl gene ENSG00000197683.
Pathways (Reactome):
Developmental Biology: Keratinization
Gene Ontology:
Molecular function: protein binding; structural molecule activity
Cellular component: cytosol; keratin filament
Genetic constraint (gnomAD): Loss-of-function variants: 0 observed, 0.38 expected, observed/expected ratio (o/e) 0, 90% interval 0 to 1.85. That is too few expected variants to judge how well the gene tolerates losing a copy. Missense variants: 273 observed, 275.28 expected, observed/expected ratio (o/e) 0.99, 90% interval 0.9 to 1.1. Synonymous variants: 111 observed, 107.59 expected, observed/expected ratio (o/e) 1.03, 90% interval 0.88 to 1.21.
Homologues: Orthologues: chimpanzee KRTAP26-1 (99% identical), mouse Krtap26-1 (55% identical), rat Krtap26-1 (52% identical). Paralogues in human: KRTAP11-1 (27% identical), KRTAP13-1 (23% identical), KRTAP27-1 (22% identical), KRTAP13-2 (21% identical), KRTAP13-3 (20% identical), KRTAP13-4 (18% identical), KRTAP15-1 (15% identical), KRTAP25-1 (10% identical).